U3 (Small nucleolar RNA U3 )
Synonyms: LOC124901507
Gene: Small nucleolar RNA gene on chromosome 6 (92,790,453 to 92,790,665, forward strand). Ensembl gene ENSG00000221455.
Gene Ontology:
Biological process: RNA processing
Cellular component: nucleolus
Homologues: Orthologues: macaque U3 (91% identical), rabbit U3 (55% identical). Paralogues in human: SNORD3E (77% identical), SNORD3P1 (73% identical), U3 (72% identical), SNORD3G (72% identical), U3 (71% identical), SNORD3H (71% identical), U3 (70% identical), U3 (69% identical), U3 (68% identical), U3 (67% identical), SNORD3D (67% identical), U3 (66% identical), and 9 more.